TNF (tumor necrosis factor)
Diseases named in the same sentence as TNF in open-access papers (continued):
Sharing a sentence is not in itself a finding about the gene and the disease.
sarcopenia (continued). "Yet another meta-analysis study, while finding that sarcopenic subjects had significantly higher levels of CRP than control subjects, showed that serum IL-6 and TNFα levels were not significantly different when people with sarcopenia were compared with controls." (PMID 34445751, 2021). "The current study showed that higher levels of systemic inflammation (as indexed by CRP) were associated with sarcopenic obesity, which is supported by a recent meta-analysis that showed that sarcopenia is associated with higher CRP, but not with higher IL-6 or TNFα." (PMID 33853546, 2021). "Furthermore, anti-TNFα therapy does not reverse sarcopenia, despite control of systemic inflammation, suggesting that other mechanisms are driving sarcopenia in RA." (PMID 34895316, 2021). "Because increases of IL6, TNFα, and MCP1 were reported as biomarkers and reasons for age-related inflammation and sarcopenia, IL10 could reduce these pro-inflammatory cytokines and mitigate age-related inflammation and sarcopenia." (PMID 30696799, 2019). "In the systemic absence of TNF‐α, sarcopenia is slowed and satellite cell numbers decline." (PMID 30256507, 2018). "Several recent studies have identified inflammatory mediators, such as IL-1, IL-6, and Tumor Necrosis Factor (TNF)-α, as contributing to the development of sarcopenia, since they may induce muscle atrophy promoting protein degradation and reactive oxygen species (ROS) accumulation." (PMID 29462978, 2018). "Meanwhile, IL-1β and TNF-α serum levels did not correlate with sarcopenia status." (PMID 30513776, 2018). "Therefore, the decreased levels of TNF, a representative pro-inflammatory cytokine, in the Ex, MSC, and MSC + Ex groups compared to the control indicate that exercise and ADMSC injections suppress inflammation, thereby facilitating the mitigation of sarcopenia." (PMID 39859165, 2025). "No specific drug therapy for sarcopenia has been established; since inflammatory cytokines such as TNFα and IL-6 produce muscle atrophy, biological agents such as TNF and IL-6 inhibitors used to treat RA may improve sarcopenia in patients with RA, but the evidence is currently limited." (PMID 37041556, 2023). "Additionally, vitamin D supplementation may decrease serum levels of the parathyroid hormone and inflammatory cytokines (i.e., TNF-α and CRP) in HF patients, therefore its supplementation is regarded as an appealing strategy to manage sarcopenia in the setting of HF." (PMID 31947528, 2020). "Of note, serum IL-4 levels were reduced, while IL-6, TNF, VEGF, and MCP-1 concentrations were increased, in patients with sarcopenia compared to those with no sarcopenia." (PMID 38001845, 2023). "There was no increased prevalence of preoperative steroids and anti-TNF treatment, penetrating phenotype of disease, hypoalbuminemia and anaemia in the group of patients with MRE defined sarcopenia." (PMID 32410158, 2021). "In fact, a recent meta-analysis of 17 cross-sectional studies involving a total of 11,249 participants confirmed that those with sarcopenia had significantly higher CRP levels than those without, while serum IL-6 levels and TNF-α were comparable in both groups." (PMID 36291982, 2022). "Serum GDF-15, TNFα and IGF-1 levels were compared in patients with and without sarcopenia." (PMID 31581569, 2019). "Proinflammatory cytokines, such as IL-6 and TNF-α, induce the production of CRP in the liver, and it has not been clarified whether high CRP level directly affects sarcopenia." (PMID 29259690, 2016). "Therefore, it is likely that the serum IL6 is a more robust predictor of physical condition in apparently healthy yet sarcopenia-prone geriatric populations, due to evidence that IL6 (but not TNFα) tends to be actively produced by the exercising muscle." (PMID 26524964, 2015).
Cerebral ischemia (406 papers, 2008 to 2026). Restriction of arterial blood supply to the brain associated with insufficient oxygenation to support the metabolic requirements of the tissue. "Both in vivo and in vitro experiments showed that Cirbp secreted by microglia after cerebral ischemia was associated with subsequent neuroinflammatory responses and neuronal damage due to Cirbp-mediated TNF-α expression." (PMID 40036292, 2025). "This activation releases numerous pro-inflammatory mediators and chemokines, including IL-6 and TNF-α, which play a role in neuronal death associated with cerebral ischemia and worsen the condition." (PMID 39996714, 2025). "In the early stages of cerebral ischemia, an increase in TNF-α release or synthesis is a principal cause of cerebral infarction." (PMID 37417988, 2024). "Cerebral ischemia can cause damage to neuronal and glial cell membranes, which results in the production of TNF-α, IL-1, and IL-6." (PMID 37569457, 2023). "Modern research shows that NF-κB is activated, leading to the excessive production of proinflammatory cytokines, including TNF-α, IL-1β, and IL-6, and inducible nitric oxide synthase, which cause inflammatory injury on the basis of cerebral ischemia." (PMID 35463086, 2022). "After cerebral ischemia injury, NFκB, activated by phosphorylated inhibitory proteins, enters the nucleus to promote the expression of iNOS and tumor necrosis factor-α, causing damage to cerebral ischemia tissue by the vicious circle." (PMID 36408103, 2022). "Cerebral ischemia also increased NF-κB, which causes the expression of IL-1, IL-6, and TNF genes that participate in brain damage." (PMID 33643574, 2021). "During the early stage of cerebral ischemia, increased TNF-α secretion or synthesis was the main cause of cerebral infarction." (PMID 34582494, 2021). "In other research, remote IPOCs can also reduce the upregulation and activation of TNF‐α and NF‐κB, caused by cerebral ischemia‐reperfusion injury, and reduce the infarct size and the number of neuronal apoptosis." (PMID 34559467, 2021). "Treatment with fucoidan (80, 160 mg/kg) inhibited MPO activity and inflammation-associated cytokines such as IL-1, IL-6, TNF-α, and attenuated cerebral ischemia-reperfusion injury." (PMID 32508671, 2020). "Cerebral ischemia is followed by an inflammatory reaction, the release of various proinflammatory cytokines, including IL-6, IL-1β and TNF-α, is the main mechanism underlying ischemic inflammatory injury." (PMID 32518214, 2020). "TNF-α is a pleiotropic cytokine that can cause leukocyte infiltration and tissue damage after cerebral ischemia." (PMID 32194375, 2020). "Following cerebral ischemia and reperfusion, many proinflammatory and cytotoxic factors, including IL-6, IL-1β, TNF-α, and NO, can cause cell injury and apoptosis." (PMID 30949500, 2019). "In this study, we demonstrated that cerebral ischemia-reperfusion injury caused elevated levels of TNF-α, IL-1β, and IL-6 in the serum." (PMID 31031621, 2019). "Proinflammatory cytokines, such as TNF-α, are released from endothelial cells, leukocytes and resident cells in the brain following cerebral ischemia injury, and inflammatory cytokines are implicated as mediators of the BBB permeability." (PMID 30319530, 2018). "It has been well documented that inflammatory-associated cytokines such as IL-6 and TNF-α play a chief role in inflammatory activation upon cerebral ischemia-reperfusion injury." (PMID 28656054, 2017). "Microglia/macrophage activation, together with elevated expression of pro-inflammatory cytokines such as IKK-β, NF-kB, TNF-α, and IL-1β, demonstrated that the warfarin-associated HT induced a neuroinflammation after cerebral ischemia." (PMID 27566245, 2016). "Overall, our results substantiate the impression that increased brain synthesis of TNFα will precipitate long-term cognitive effects and contribute to higher risk of dementia after cerebral ischemia." (PMID 27144978, 2016).
Cerebral ischemia (continued). "Our findings is first time to show the protective effects of BMSCs in brain ischemia induced lung injury, which is linked to the inhibition of TNF-α expression." (PMID 26931747, 2016). "In particular, increased IL-1β, IL-6, and TNFα concentrations were linked to a poor prognosis in infants suffering from ischemic encephalopathy." (PMID 27565558, 2016). "The observed in vivo neuroprotection by 6-paradol is associated with the reduced expression of iNOS and TNF-α, both of which are well-known pathogenetic components in cerebral ischemia even though there is debate regarding the latter." (PMID 25789481, 2015). "Consistent with the well established induction of pro-inflammatory cytokines by cerebral ischemia, HI produced a marked elevation of mRNAs encoding TNFα, IL-1β and IL-6 (Veh-HI)." (PMID 23251498, 2012). "Excessive glutamate signalling during cerebral ischemia has been implicated in the development of excitotoxicity, while hightened TNF-α signalling mediates an inflammatory response which is known to exacerbate this detrimental glutamate response." (PMID 21810263, 2011). "Furthermore, it has recently been shown that the inhibition of PI3Kδ which is encoded by the Pik3cd gene alleviates brain injury during cerebral ischemia–reperfusion via suppressing pericyte contraction in a TNF-α-dependent manner." (PMID 40076966, 2025). "Both focal and global brain ischemia is associated with the expression of various inflammatory cytokines such as interleukin-1 (IL-1) and tumor necrosis factor-alpha (TNF-α), as well as chemokines like IL-8, monocyte chemoattractant protein-1 (MCP-1), RANTES, and IP-10." (PMID 38672167, 2024). "Eventually, it proved that sympathetic system excitation after cerebral ischemia and inducing the secretion of proinflammatory cytokines (TNF-α and MCP-1) from adipose tissue may be an underlying mechanism for the disorder of glucose metabolism in rats." (PMID 36950100, 2023). "In addition, previous studies in our laboratory have confirmed that DOR activation can inhibit the increase in TNF-α caused by cerebral ischemia–reperfusion and protect neurons from death in vivo and in vitro." (PMID 36457949, 2022). "Studies have shown that Cel can reduce focal cerebral ischemia‐reperfusion injury in rats, and the underlying mechanism may involve the inhibition of NF‐κB activation, the expression of TNF‐α and IL‐1β, and the subsequent reduction of inflammation." (PMID 33282271, 2020). "Cerebral ischemia and reperfusion injury result from the rapid and explosive reoxygenation induced by the inflammatory response, which is tightly associated with inflammatory mediators such as IL-1β, TNF-α, and IL-6." (PMID 29867706, 2018). "Although TNFα is well recognized as an inflammatory mediator that may enhance neuronal loss after cerebral ischemia, recent evidence suggests that it may have an alternate, beneficial role in augmenting neural recovery." (PMID 27144978, 2016). "The objective of this study was to determine whether ETN-induced inhibition of TNF-α biological activity could improve brain damage caused by cerebral ischemia in streptozotocin- (STZ-) induced diabetic rats." (PMID 26665003, 2015). "Furthermore, TNF-α has been implicated in the pathogenesis of several central nervous system disorders, including cerebral ischemia, Parkinson's disease, and brain injury, as central mediators of tissue injury and inflammation." (PMID 26665003, 2015). "Furthermore, target genes of NF-κB have been implicated in the pathogenesis of cerebral ischemia, such as IL-1, IL-6, TNF-α, ICAM-1, MMP9, COX-2, and iNOS." (PMID 24624056, 2014). "In the present study, the heat stroke-induced increases in arterial hypotension, cerebral ischemia and neuronal damage are associated with elevated levels of DA, 5-HT, glutamate and hydroxyl radicals in rat brain, and increased circulating IL-1β, TNF-α and MDA in the peripheral blood stream." (PMID 20937119, 2010).
Cerebral ischemia (continued). "Compared with the control, the level of TNF-α in the AR group significantly decreased after treatment (p < 0.05), which suggested that the neuroprotective effects of AR may be related to the inhibition of neurogenic inflammation caused by cerebral ischemia." (PMID 37361203, 2023). "Although these data support the neuroprotective benefits of inhibiting TNF-alpha, TNF or TNF-receptor deficient mice showed larger infarctions and worse outcomes than non-genetically modified mice, supporting the neuroprotective role of TNF in cerebral ischemia." (PMID 32357544, 2020). "Utilizing the novel resource of the TNFα-Tg rat, we tested the hypothesis that elevated brain levels of TNFα protein will undermine hippocampal synaptic integrity or contribute to enhanced neuronal loss after cerebral ischemia, thereby worsening cognitive or functional impairment." (PMID 27144978, 2016). "The S100B/RAGE-induced upregulation of NO and TNF-α synthesis in neurons and glial cells causes oxidative stress and neuronal apoptosis, leading to cerebral infarct expansion, which plays a pivotal pathological role during the subacute phase of cerebral ischemia." (PMID 24626220, 2014). "Microglia and astrocytes are activated within minutes after cerebral ischemia and release some pro-inflammatory factors, such as TNF-α, NF-κB, IL-1β, and IL-6." (PMID 41329542, 2025). "Cerebral ischemia triggers diffusion impairment of the blood-brain barrier, concomitant with an accumulation of pro-inflammatory mediators (TNF-α, IL-1β, IL-6) within the brain and serum, provoking an inflammatory cascade." (PMID 40144659, 2025). "Corroborating these insights, our research unveiled heightened TNF-α, IL-1β, and IL-6 concentrations in hippocampal and prefrontal cortical tissues post-cerebral ischemia." (PMID 40144659, 2025). "Cerebral ischemia and neuroprotection: In the rat I/R model, higenamine can improve neurological function and inhibit I/R-induced serum tumor necrosis factor α (TNF-α) and interleukins (such as IL-1 and IL-6)." (PMID 40290051, 2025). "Studies have shown that neuroinflammation and cerebral ischemia are mediated by the secretion of IL‐1α, TNF‐α, and complement 1q (C1q) by classically activated microglia (M1 type)." (PMID 41395456, 2025). "During the initial phase of cerebral ischemia and hypoxia, neutrophils are activated by the substantial secretion of cytokines, including tumor necrosis factor (TNF), interleukin-1β (IL-1β), and interleukin-8 (IL-8)." (PMID 40689325, 2025). "The cGAS/STING/IRF3 pathway mediates neuroinflammation during cerebral ischemia, where hyperactivation promotes excessive production of proinflammatory cytokines (e.g., TNF-α, IL-6) and chemokines, exacerbating cerebral damage." (PMID 41471264, 2025). "Tangeretin exhibits potent anti-inflammatory properties by reducing proinflammatory cytokines, TNF-α and IL-6, in rats exposed to cerebral ischemia and murine macrophage RAW264.7 cells." (PMID 40141836, 2025). "Brain ischemia induced significant elevations in plasma levels of the pro-inflammatory TNF-α, IL-6, and IL-1β, which were significantly mitigated by 3-MP." (PMID 40095189, 2025). "The predominance of upregulated downstream targets (red nodes) suggests that TNFα drives a pro-inflammatory transcriptional program following brain ischemia and that PPARα normally suppresses this response." (PMID 40362325, 2025). "Allicin has been found to have an anti-inflammatory pathway and neuroprotective impact against brain ischemia, leading to significant reductions in the levels of TNF-α and MDA." (PMID 39827123, 2025). "Cerebral ischemia and hypoxia injury can stimulate monocytes to generate interleukin-6 (IL-6), tumor necrosis factor (TNF), and other inflammatory mediators, which further aggravate cerebral ischemia and hypoxia." (PMID 39634770, 2024).
Cerebral ischemia (continued). "We also identified significant increases in NF-κB, TNF-α, and IL-1β in cerebral ischemia, and retinoic acid significantly alleviated these increases." (PMID 38527023, 2024). "In conclusion, our findings demonstrated that M2 microglial EVs attenuated BBB disruption after cerebral ischemia by delivering miR-23a-5p, which targeted TNF and regulated MMP3 and NFκB p65 expression." (PMID 37611902, 2024). "Cerebral ischemia induced a transient increase of TNF, IL-1β, IL-6, CXCL1, and CCL5 at day 1 post-pMCAO, corresponding to the peak of pro-inflammatory cytokines typically observed in this model." (PMID 38142915, 2024). "Inhibiting TNF‐α in mouse models of cerebral ischemia/reperfusion decreased cerebral infarction and improved the functional outcomes." (PMID 37789643, 2024). "In the early stage of ischemic brain injury disease, cerebral ischemia/reperfusion injury induces macrophages to secrete IL-1β and TNF-α, activate white blood cells, and generate inflammatory response." (PMID 38927572, 2024). "Cerebral ischemia resulted in significantly increased levels of IL-1β, IL-6, and TNF-α compared with those after sham treatment." (PMID 37812268, 2024). "The mechanistic study revealed that M2 microglial EVs attenuated BBB disruption in the acute stage of cerebral ischemia by delivering miR-23a-5p, which targeted TNF and regulated MMP3 and NFκB p65 expression." (PMID 37611902, 2024). "Following cerebral ischemia, inflammatory processes are initiated, with microglia and astrocytes releasing pro-inflammatory cytokines like IL-1β, TNF-α, and IL-6." (PMID 39625909, 2024). "This study established the first evidence of Mxene-bpV’sneuroprotective effects against cerebral ischemia-reperfusion injury via a reduction in the levels of pro-inflammatory cytokines, including IL-1β, IL-6 and TNF-α." (PMID 39073469, 2024). "The treatment of COST resulted in a reduction in the level of TNF-α in a rat model of cerebral ischemia." (PMID 38629103, 2024). "During cerebral ischemia, the expression of both pro-inflammatory, as TNF-α, IL-1β, IL-6, and anti-inflammatory cytokines, MCPIP1, rapidly increases throughout the brain tissue." (PMID 37812268, 2024). "Considerable evidence showed that the Fas, FasL, and TNF-mediated extrinsic apoptotic signaling cascade plays an important role in neuronal cell death after cerebral ischemia." (PMID 39273389, 2024). "In the brains of ASK1-deficient mice, decreased activation of microglia and reduced levels of TNFα, IL-6, and IL-1β were observed following brain ischemia." (PMID 39008037, 2024). "Sesamol also reduced the mRNA expression of different proinflammatory factors such as TNF-α in cerebral ischemia." (PMID 37333469, 2023). "In both rodent models and human patients, microglia/macrophages have been recognized as a main source of TNF-α during the early stages of cerebral ischemia." (PMID 36890539, 2023). "Cerebral ischemia can induce an increase in both mRNA and protein expression levels of TNF‐α in the lung tissues of rats with lung injury." (PMID 38680513, 2023). "PTX decreased TNF-α and NF-κB in cerebral ischemia reperfusion, high-fat-diet-induced nonalcoholic fatty liver, and diclofenac-induced acute renal injury models." (PMID 37628836, 2023). "For example, cerebral ischemia and hypoxia can stimulate monocytes to yield inflammatory mediators: interleukin-6 (IL-6) and tumor necrosis factor (TNF), exacerbating cerebral ischemia and hypoxia, resulting in more extensive cerebral tissue destruction." (PMID 37616313, 2023). "Cerebral ischemia produces great amounts of proinflammatory factors such as TNF-α and IL-1β and inhibits the production of anti-inflammatory factors such as IL-10 and IL-449." (PMID 37132753, 2023). "In a recent study, we observed that KLF4 inhibited TNF-a-induced activation of NF-kB to alleviate the cerebral ischemia-induced cerebral vascular inflammation." (PMID 36823628, 2023).